HMGA1 (high mobility group AT-hook 1)
Diseases named in the same sentence as HMGA1 in open-access papers (continued):
Sharing a sentence is not in itself a finding about the gene and the disease.
cancer (continued). "Analysis of 36 cancer types revealed that HMGA1 expression significantly correlates with altered infiltration of various immune cells, including B cells, T cells, macrophages, neutrophils, and dendritic cells." (PMID 41463532, 2025). "Database searches indicated that NAT1, BIRC3, EZH2, MAD2L1, ATP2A3, HMGA1, and BST2 are cancer-associated genes." (PMID 41255601, 2025). "The links between HMGA1 overexpression with tumor growth and development, drug resistance, poor prognosis and direct role in cancer development are well established." (PMID 41183073, 2025). "Previous studies have shown that HMGA1 supports oncogenic transformation, epithelial–mesenchymal transition, and metastasis in many cancers." (PMID 41463532, 2025). "This gap underscores the need for our study, which focuses specifically on defining the role of DNA hypomethylation in driving HMGA1 overexpression across human cancers." (PMID 41463532, 2025). "Building on this observation, we developed an adenoviral vector containing exogenous DNA with an HMGA1 hyper binding site (HBS) capable of delivering multiple HMGA1 sequestration sites directly to cancer cells." (PMID 41183073, 2025). "Overexpression of HMGA1 in both human and murine cancer cells has been shown to enhance colony formation, as well as promote cancer cell invasion and metastasis, making it a negative prognostic modulator." (PMID 41145488, 2025). "For instance, HMGA1, a chromatin structural protein, is highly overexpressed in malignant tumours and has been shown to promote tumour growth by increasing cell proliferation and survival, disrupting DNA repair, and causing chromosomal instability." (PMID 39828988, 2025). "HMGA1 becomes reexpressed in aggressive cancer cells and high levels portend adverse clinical outcomes." (PMID 39895630, 2025). "To strengthen the bulk transcriptomic findings at cellular resolution and establish the pan-cancer relevance of HMGA1-driven immune evasion, we performed comprehensive single-cell RNA sequencing analysis across six malignancies." (PMID 41463532, 2025). "We found that HMGA1 was markedly upregulated in most cancers, mainly driven by promoter hypomethylation and copy number alterations." (PMID 41463532, 2025). "We also identified strong positive associations between HMGA1 expression and TMB and MSI in several cancer types, along with correlations with mismatch repair gene expression." (PMID 41463532, 2025). "Among these, there were known regulators such as HOXB2 and KLF4 in Cancer LumA, as well as HMGA1 in Cancer Basal." (PMID 40397381, 2025). "Our analysis confirmed that HMGA1 is broadly overexpressed in cancer tissues compared to matched normal controls and that this upregulation is mainly derived by promoter hypomethylation and copy number amplification." (PMID 41463532, 2025). "This pattern of HMGA1 overexpression in cancer cells was further validated using another publicly available dataset, strengthening its relevance as a target for further studies." (PMID 41145488, 2025). "Studies have demonstrated SP-D’s selective apoptotic effect on cancer cells with elevated High-Mobility Group A1 (HMGA1) expression, an oncogenic transcription factor overexpressed in various high-grade malignancies, while sparing healthy cells." (PMID 39742280, 2024). "In this regard, we believe that the expression of HMGA1 in ESCC effectively affects the sensitivity of cancer cells to ferroptosis." (PMID 38383528, 2024). "HMGA1 is highly expressed in multiple malignancies and correlates with poor prognosis of cancer patients." (PMID 39080260, 2024). "In contrast, depletion of HMGA1 not only inhibits cancer cell proliferation but also induces programmed cell death, sensitizing cancer cells to chemotherapy." (PMID 38383528, 2024).
cancer (continued). "The similar gene expression changes and protein binding profile of HMGA1 observed in H1299 cells open exciting avenues for investigating the impact of HMGA1 in cancer." (PMID 39134516, 2024). "Overexpressed in several aggressive cancers, HMGA1 functions as a master regulator of gene expression, influencing cellular processes such as transcription, cell cycle progression, differentiation, DNA repair, and neoplastic transformation." (PMID 39596391, 2024). "HMGA1 also displayed increased activities and was linked with epithelial‒mesenchymal transition (EMT) and cancer cell stemness through transcriptional and post‐transcriptional interactions." (PMID 39187937, 2024). "The elevated mRNA expression of HMGA1/A2/B1/B2/N2/N3 in tumor tissues exhibited correlation with the cancer stages of HCC patients." (PMID 39591457, 2024). "Inhibiting HMGA1 expression with SP-D disrupts oncogenic signalling pathways that support cancer cell survival, ultimately leading to apoptosis and inhibition of cancer cell growth." (PMID 39742280, 2024). "As a transcription factor, HMGA1 activates the expression of numerous cancer-promoting genes while inhibiting the expression of various apoptosis-related genes, thus enhancing cancer cell resistance to apoptosis." (PMID 39610830, 2024). "In certain cancer cells, HMGA1 can activate the PI3K/Akt signaling pathway and upregulate the expression of matrix metalloproteinase 9 (MMP-9)." (PMID 39507236, 2024). "HMGA1 is positively correlated with the degree of cancer progression and an unfavourable marker for clinical prognosis." (PMID 39080260, 2024). "When overexpressed in lymphoid cells of transgenic mice, Hmga1 induces aggressive leukemia by upregulating transcriptional networks active in proliferating stem cells, poorly differentiated cancer cells, and inflammation." (PMID 36919699, 2023). "Several unique markers, including HMGA1, were identified for metastasis-enriched cancer cell subpopulations." (PMID 37190324, 2023). "We further validated the upregulated expression level of HMGA1 in cancer cells from liver metastases, in comparison to primary tumors, using immunohistochemistry staining on tissue sections from both transgenic mice and human patients." (PMID 37190324, 2023). "HMGA1 is aberrantly expressed in various cancers and represents a potential target for cancer treatment." (PMID 36635290, 2023). "Next, we conducted in vitro experiments and identified that siRNA-mediated knockdown of Hmga1 significantly suppressed the cell viability of KPC cancer cells, consistent with recent findings." (PMID 37190324, 2023). "Further analysis of the biological effects of their high correlation in cancers suggested that cell cycle was the most significant related pathway commonly regulated by HMGA1 and FOXM1." (PMID 37240870, 2023). "Pearson correlation analysis displayed that expression of HMGA1 was positively correlated with that of FOXM1 in all analyzed cancer samples in TCGA databases from GEPIA (r = 0.67, p = 0)." (PMID 37240870, 2023). "Based on the cancer cell-specific, metastasis-related markers revealed by our prior results, we further tested the expression of HMGA1 as a proof of concept because of the direct availability of validated antibodies by the Human Protein Atlas database." (PMID 37190324, 2023). "In this study, we found that HMGA1 was overexpressed and predicted poor clinical outcomes in most types of cancers." (PMID 37240870, 2023). "We also identified several unique markers, including HMGA1, that were upregulated in cancer cell subpopulations of liver metastases." (PMID 37190324, 2023). "It has been reported that the dysregulation of HMGA1 was correlated with the cancer drug-resistant phenotype." (PMID 36760722, 2023). "The high mobility group A1 (HMGA1) gene is overexpressed in malignant tumors, and its expression level correlates with the progression and metastasis of tumors." (PMID 36705364, 2023).
cancer (continued). "Existing studies have revealed that miR-26a and its target HMGA1 are involved in the pathological progress of many cancers." (PMID 36820066, 2023). "HMGA1 was selected for further investigation because it was reported to be overexpressed in OC and correlated with cancer progression." (PMID 36776216, 2023). "High mobility group AT-hook 1 (HMGA1) is a structural transcription factor that acts as a tumor promotor in a variety of cancers where it is overexpressed, including hepatocellular, pancreatic, colorectal, and gastric." (PMID 36978140, 2023). "HMGA1 can also promote cancer stemness and epithelial-mesenchymal transition of perihilar cholangiocarcinoma via modulation of c-Myc." (PMID 35785026, 2022). "The HMGA1 expression level was successfully determined in 28 blood samples collected at the time of diagnosis of cancer, 21 blood samples collected 100 days after the surgery, and 11 blood samples collected 1 year after the surgery." (PMID 35948739, 2022). "Mean HMGA1 expression level in blood decreased systematically from the time of cancer diagnosis to 1 year after surgery." (PMID 35948739, 2022). "HMGA1 activates the expression of the SAC gene, which also illustrates a new mechanism of HMGA1 overexpression leading to cancer." (PMID 35864955, 2022). "We found that human cancer clusters showed specific gene expression patterns for high-mobility group AT-hook 1 (HMGA1) and CD44." (PMID 35611554, 2022). "NSCLC patients with higher staining of the HMGA1 in cancer tissue had worse OS than those the lower staining." (PMID 35948739, 2022). "We did not state a significant connection between the clinical advancement of the cancer disease and blood HMGA1 expression level." (PMID 35948739, 2022). "As shown by scatter plots, a significantly decreased Let‐7a expression was observed in cancer tissues compared to that in normal tissues (p < 0.05), HMGA1 and LINC00152 were highly expressed in cancer tissues." (PMID 35014092, 2022). "Previously, accumulated data pointed the regulatory roles of HMGA1 in cancer cell proliferation, invasion, metastasis, stemness, and drug resistance through multiple mechanisms, including HCC." (PMID 35785026, 2022). "The results showed significant correlations between HMGA1 and the 28 types of TILs found in human cancers." (PMID 35014092, 2022). "In this review, we summarize the mechanisms of HMGA1 in cancer progression and discuss the potential clinical application of targeted HMGA1 therapy, indicating that targeted HMGA1 is of great significance in the diagnosis and treatment of malignancy." (PMID 35864955, 2022). "HMGA1 has been confirmed to be related to a variety of cancers, and the expression of HMGA1 was significantly upregulated in various cancers." (PMID 35459188, 2022). "Our data show that HMGA1, affecting the expression of RD-HIST, acts on a fundamental process that is intrinsically linked to the proliferative ability of cancer cells." (PMID 36614035, 2022). "HMGA1 also drives neoplastic transformation, anti-apoptosis, angiogenesis as well as immune evasion in cancer." (PMID 36685838, 2022). "Overexpressed HMGA1 blocks the cell cycle and accelerates the proliferation and migration of cancer cells." (PMID 35864955, 2022). "Normally, the expression level of HMGA1 is very low, but HMGA1 is a cancer‐promoting gene that is overexpressed in many malignant tumors." (PMID 35014092, 2022). "The qRT-PCR and western blot results showed higher HMGA1 expression in cancer tissues comparing with that in normal adjacent tissues." (PMID 36479041, 2022). "In conclusion, we provide evidence that highlights a role of HMGA1 in controlling the expression of RD-HIST genes with implications in the cell-cycle of cancer cells." (PMID 36614035, 2022). "Based on publicly available cancer data, HMGA1 was shown to be overexpressed in both SCLC and NSCLC, with higher expression compared to both the adjacent non-malignant lung tissues and non-tumor lung tissues of healthy individuals." (PMID 35948739, 2022).
cancer (continued). "In analysis of RNA-seq data in TIMER database, we found that the expression of HMGA1 in most cancer tissues was higher than that in normal tissues, including breast and other 17 types of cancers." (PMID 36479041, 2022). "HMGA1 has been confirmed to affect malignant tumours and has the potential to be a useful biomarker for the diagnosis and treatment of malignant tumours." (PMID 35864955, 2022). "HMGA1, as an architectural transcription factor, reshapes chromatin structure in different cancers and promotes the interaction between transcriptional regulatory proteins and DNA." (PMID 35082972, 2022). "Little is known about the role of HMGA1 mutations in determining the function and expression level of the HMGA1 in cancer." (PMID 35805937, 2022). "HMGA1 is a protein closely related to tumor growth, infiltration, and metastasis and is highly expressed in various cancers." (PMID 35014092, 2022). "Consistent with the previous reports, HMGA1 was frequently overexpressed in human cancers, including liver hepatocellular carcinoma (LIHC)." (PMID 35785026, 2022). "Collectively, our data provided a new mechanism of HMGA1-induced progression of tumor and indicated a new treatment approach to CCA and other the HMGA1-overexpressing cancers." (PMID 33648560, 2021). "The exosomal lncRNA HOTTIP, transmitted from cisplatin-resistant gastric cancer cells to sensitive cancer cells, plays a role in conferring cisplatin resistance to sensitive cancer cells by binding to miR-218 to activate HMGA1." (PMID 33718365, 2021). "HMGA1 is involved in cellular activation, including that related to insulin activity and cancer cell proliferation." (PMID 34072941, 2021). "When overexpressed in lymphoid cells of transgenic mice, Hmga1 induces aggressive leukemia by up-regulating transcriptional networks active in rapidly proliferating stem cells, poorly differentiated cancer cells, and inflammation." (PMID 34572547, 2021). "HMGA1 is enriched in aggressive cancers and stem cells, and c-Myc is one of the four well-known Yamanaka factors influencing stemness." (PMID 33648560, 2021). "Here, we review the role of HMGA1, not only as a chromatin regulator in cancer and stem cells, but also as a potential secreted factor that drives tumor progression." (PMID 34572547, 2021). "Until recently, HMGA1 was assumed to be a nuclear protein exerting its role in cancer by transcriptionally modulating different signaling pathways." (PMID 34572547, 2021). "HMGA1 is strongly expressed during embryogenesis and in virtually all aggressive human cancers but is silenced in adult, differentiated tissues." (PMID 34167089, 2021). "Based on the link between inflammation and cancer, HMGA1- NF-κB complexes, also known as the HMGA1 enhanceosome, are likely to contribute neoplastic transformation." (PMID 34572547, 2021). "HMGA1 has been shown to contribute to the maintenance of cancer stem cell populations and promote cell proliferation, angiogenesis and anchorage-independent growth." (PMID 34831413, 2021). "Using StarBase database, we found HMGA1 to be the direct target of miR-324-5p, and HMGA1 has oncogenic activity in multiple cancers, including GC." (PMID 34483139, 2021). "HMGA1 is especially involved in the proliferation and invasion of activated cells, such as cancer cells." (PMID 34072941, 2021). "Until recently, HMGA1 was assumed to be a nuclear protein exerting its role in cancer by transcriptionally modulating gene expression and downstream signaling pathways." (PMID 34572547, 2021). "Growing evidence indicates that HMGA1 is an important oncoprotein and ectopic expression of HMGA1 is correlated with unfavorable outcomes of patients in cancer." (PMID 34167089, 2021). "Prior studies of HMGA1 in cancer and development focused on its role in the nucleus as a regulator of chromatin structure and function." (PMID 34572547, 2021).
cancer (continued). "In the literature, there are several reports in cancer cell lines describing the role of HMGA1 expression in conferring resistance to antineoplastic drugs, including in GC." (PMID 35049679, 2021). "High mobility group A1 (HMGA1) is an architectural transcription factor that is overexpressed in multiple malignant tumors." (PMID 34716319, 2021). "The activation of MMP-2 and MMP-9 by HMGA1 and the interaction of these MMPs are reportedly important for the growth and invasion of cancer cells in malignant tumors and those of EVTs in the placenta." (PMID 34072941, 2021). "Based on existing knowledge, we discuss the potential consequences of cross-talk between the nuclear and extracellular HMGA1 in cancer biology." (PMID 34572547, 2021). "We have recently identified and characterized two pseudogenes (HMGA1P6 and HMGA1P7) of the HMGA1 gene, which has a critical role in malignant cell transformation and cancer progression." (PMID 32341372, 2020). "miR-16 is considered to be a critical tumour suppressor miRNA downregulated in many types of cancer, among the validated miRNAs targeting both HMGA1 and HMGA2." (PMID 31979076, 2020). "Accordingly, it has been shown that high levels of HMGA1 expression play a central role in driving cancer progression and aggressiveness." (PMID 33536877, 2020). "HMGA1P6 and HMGAP17 act as microRNA decoy for HMGA1 and other cancer-related genes upregulating their protein levels." (PMID 32341372, 2020). "While several TFs, e.g. HMGA1, a chromatin re-modeller which is known to be highly active in cancer, have a positive regression coefficient, indicating an activatory role of those TFs, we see that several TFs are assigned a negative regression coefficient." (PMID 32029002, 2020). "Here, we used an approach that considered the genomic location, as well as the known function of neighboring oncogenic protein-coding genes, to find and characterize a novel cis-acting lncRNA deregulated in cancer, which we refer to as HMGA1-lnc." (PMID 33505435, 2020). "HMGA1/2 overexpression is a frequent event in human malignancies, and correlates with cancer progression, high aggressiveness, and poor prognosis." (PMID 32127525, 2020). "As an architectural transcription factor, HMGA1 remodels the chromatin structure and promotes the interaction between transcriptional regulatory proteins and DNA in different cancers." (PMID 30614613, 2019). "HMGA1 has been a promising cancer drug candidate for years, but, being a nuclear protein, it was nearly impossible to target it." (PMID 31779212, 2019). "Further work has to be done to in–deep evaluate the role of HMGA1 in influencing the epigenetic status of cancer cells." (PMID 31382504, 2019). "We previously demonstrated the pivotal role of HMGA1 in conferring several cancer hallmarks in TNBC, showing that HMGA1 is involved in modulating an intricate molecular network." (PMID 31311575, 2019). "HMGA1 is usually expressed at very high level in cancer cells (up to a ratio of 1/5 with histone H1." (PMID 31382504, 2019). "Overall, it appears that HMGA1 has an important role in cancer, that HMGA1 expression is increased in cancer, and that elevated HMGA1 expression serves as a predictor of poor clinical prognosis." (PMID 30614613, 2019). "Studies indicated that overexpression of HMGA1 can elevate Spheroid‐forming cancer stem cells, increasing stemness‐related gene expression, such as ALDH, SOX2, ABCB1, ABCG2 and KLF4." (PMID 30614613, 2019). "A thorough review of the HMGA1 literature in cancer research was out of the scope of this review; instead, we refer readers to the following excellent reviews on this topic." (PMID 31779212, 2019). "HMGA1 overexpression is correlated with poor clinical outcome, distant metastasis and advanced tumour stage in many cancers." (PMID 30614613, 2019).